NRP1 (neuropilin 1)
Diseases named in the same sentence as NRP1 in open-access papers (continued):
Sharing a sentence is not in itself a finding about the gene and the disease.
cancer (470 papers, 2003 to 2026). A tumor composed of atypical neoplastic, often pleomorphic cells that invade other tissues. "Neuropilin-1 (NRP-1) was originally associated with the evolution of the nervous system, but increasing evidence indicates its important role in cancer, particularly in angiogenesis, chemoresistance and other aspects of malignant progression." (PMID 40430075, 2025). "NRP1 gene amplification and mutations have been detected in certain cancers, contributing to aberrant expression and activity." (PMID 40277760, 2025). "NRP1+ Treg cells are more prevalent in malignancies in cancer patients, and therapeutic intervention is linked to a reduction in NRP1 expression in peripheral Treg cells." (PMID 40277760, 2025). "Single Nucleotide Polymorphisms (SNPs): Specific SNPs in the NRP1 gene have been linked to cancer susceptibility and prognosis." (PMID 40277760, 2025). "NGF is implicated in inflammatory, neuropathic, surgical, and cancer pain, highlighting the need to study contributions of NRP1 across pain pathologies." (PMID 39589827, 2024). "Our study underscores the crosstalk between TNBC cells and TAMs mediated by VEGFA and further clarifies the role and underlying mechanisms of the VEGFA/NRP-1/GAPVD1 axis in regulating cancer stemness." (PMID 38169627, 2024). "We analyzed cell morphology, migration, and the expression of neuropilin 1 (NRP1), a receptor involved in angiogenesis, cell migration, and extracellular matrix remodeling, known to be associated with cancer progression and poor prognosis." (PMID 38903533, 2024). "Neuropilin‐1 (NRP1) is another feature protein expressed by Treg cells, and surface NRP1 level was linked to an increasing number of intratumoural Treg cells and reduced survival in cancer patients." (PMID 37403792, 2023). "Neuropilin-1 (NRP1), encoded by the NRP1 gene, is a transmembrane glycoprotein overexpressed in several types of cancer." (PMID 37511358, 2023). "With this comprehensive understanding, there are strong reasons to believe that NRPs, especially NRP1, are attractive diagnostic and prognostic biomarkers that mediate immunoregulation and have functions beyond immunology in the context of cancer." (PMID 37190154, 2023). "Our study suggested that NRPs, especially NRP1, are attractive diagnostic and prognostic biomarkers, mediate immunoregulation, and have functions beyond immunology in the context of cancer." (PMID 37190154, 2023). "NRP1 was closely associated with a variety of genes in pan-cancer studies, such as IGF-1, PDIA3, and CD36." (PMID 37450415, 2023). "NRP1 is also involved in the cell proliferation, migration, and invasion associated with cancer progression." (PMID 36389678, 2022). "Above results indicated that mRNA expression level, protein expression level, and mutation rate of NRP1 in different cancer types varied a lot." (PMID 36338984, 2022). "In summary, the CD44 and NRP1 inhibitors to treat cancer patients with high-risk scores are promising." (PMID 36389678, 2022). "NRP1 has recently been implicated in resistance to cancer therapies including oncogene-targeted therapies and chemotherapy through activation of bypass survival pathways, including receptor-tyrosine kinase pathways such as HER2, EGFR and IGF1R." (PMID 35078508, 2022). "This has been associated with the NRP1-derived induction of angiogenesis that leads to oxygen and nutrients supply to the cancer cells." (PMID 35884516, 2022). "Functional vascular tree formation is a key step in many contexts, such as cancer, and Neuropilin1 (NRP1) has been associated with adhesion receptor endocytic turnover." (PMID 35858913, 2022). "According to the disease and function analysis, we found that NRP1 knockdown is associated with many malignant tumor-related functions." (PMID 34249735, 2021). "In the past years, NRP-1 has also been associated with malignant transformation and cancer progression." (PMID 33884469, 2021).
cancer (continued). "There is increasing evidence had indicated that higher expression of NRP1 associated with diverse malignant tumors of human, including hepatocellular carcinoma, breast cancer, gastric cancer, and prostatic cancer." (PMID 32472711, 2020). "Both splice variants were identified in colorectal cancer, with NRP1-ΔE4 expression correlating with cancer progression." (PMID 32388640, 2020). "It is believed that this phenomenon is caused by an autocrine pathway through the VEGF165/NRP-1 axis, which favors cancer cells’ migration, proliferation, and growth, and also increases their survivability." (PMID 31064153, 2019). "NRP1 is involved in regulation of a variety of cellular functions, such as cell proliferation, migration and invasion associated with cancer progression." (PMID 31420553, 2019). "High levels of Nrp1 have been associated with poor outcome in patients with cancers of various origins and correlated with invasive behavior and metastatic potential." (PMID 30360368, 2018). "The precise signaling pathways of NRP-1 action are still unclear as they interact with many cancer associated molecules." (PMID 29632646, 2018). "Alterations of NRP1 glycosylation, induced enzymatically or by mutations of Ser612, profoundly alter cancer cells phenotype." (PMID 27798666, 2016). "NRP-1 has been strongly associated with additional growth-factors, suggesting a positive feedback loop that allows the induction of cancer-promoting properties through the respective receptors." (PMID 26701889, 2016). "We decided to further explore the possibility of antagonizing signaling partners of NRP1 by interfering with hetero-association of NRP1 with other important cancer associated receptors." (PMID 27506939, 2016). "NRP-1 is overexpressed in many cancer cell lines, where it is implicated in migration, proliferation, and survival." (PMID 23986882, 2013). "Up-regulated NRP-1 has been shown to be associated with carcinomas of various tissues including lung, breast, prostrate etc.." (PMID 23185562, 2012). "Metabolite Biomarkers: Changes in the metabolite profiles associated with NRP1 activity may serve as biomarkers for cancer diagnosis and prognosis." (PMID 40277760, 2025). "Genomic studies have identified alterations in the NRP1 gene that are associated with cancer." (PMID 40277760, 2025). "To explore the mechanism underlying this effect, we first assessed whether the gene-delivery capacity of PEI-elastase was associated with NRP1, which had previously been shown to mediate elastase uptake by cancer cells." (PMID 39068444, 2024). "In terms of diagnostic and prognostic applications, NRP1 has shown promise across various cancers." (PMID 39334861, 2024). "To analyze whether substrate stiffness modulates the expression of NRP1, a protein associated with cancer progression, we analyzed NRP1 mRNA expression in four different cell lines following 24 h of culture on PAA hydrogels." (PMID 38903533, 2024). "Several investigations have revealed that NRP1 may be a crucial modulator of angiogenesis and cell migration, key processes involved in the loss of chemosensitivity in cancer, mostly to antiangiogenic drugs." (PMID 36376373, 2023). "Neuropilin 1 (NRP1), a cell-surface co-receptor of a number of growth factors and other signaling molecules, has long been the focus of attention due to its association with the development and the progression of several types of cancer." (PMID 37513474, 2023). "Besides, we did a pan-cancer analysis of the relationship between NRP1 expression and OS, NRP1 mutation, and TME." (PMID 36338984, 2022). "We found that expression level and mutation rate of NRP1 depended on cancer types." (PMID 36338984, 2022). "Notably, NRP1, a known co-receptor of Sema3C, has been repeatedly implicated in cancer cell resistance to therapy." (PMID 33537086, 2021). "All these together established a strong association between NRP1 and cancer." (PMID 34961486, 2021).
cancer (continued). "Neuropilin‐1 (NRP‐1) was involved in the progress of many cancers, it is found overexpressed in hepatocellular carcinoma, colorectal cancer, glioblastoma, and lung cancer, and its expression associated with advanced cancer stages and poor prognosis." (PMID 32951327, 2020). "To determine whether the NRP1 variants facilitate cancer metastasis, we used an experimental lung metastasis model in vivo." (PMID 31420553, 2019). "Thus, although an overall high level of NRP1 expression in cancer is associated with an unfavorable prognosis 14, 15, 16, 17, the exact distribution of NRP1 on different cell types in the cancer dictates its effect on disease progression." (PMID 30027561, 2018). "Furthermore, elevated HGF, a ligand for c-met and NRP-1 that is involved in epithelial-mesenchymal transition and metastatic behavior of cancer cells was significantly associated with NRP-1 expression." (PMID 26701889, 2016). "Future studies could also examine the cross-reactivity of available mAbs against neuropilin-1, considered by some to be a superior marker and implicated in Treg-mediated suppression within certain cancer microenvironments." (PMID 25119018, 2014). "This was confirmed in Nrp1-deficient T cells, which performed similarly to wild-type T cells within both immune and tolerant environments, and when used in adoptive immunotherapy for cancer." (PMID 25343644, 2014). "Bae and colleagues describe that autophagy, which was induced by administration of Rapamycin, associated with a reduction in the expression of Nrp1 on the surface of endothelial and carcinoma cells, which is somewhat counter-intuitive with a direct intracellular synergistic effect." (PMID 23577203, 2013). "The identification of the mechanisms underlying increased sensitivity to NRP1 disruption in ECs with reduced β3-integrin expression should enable the rational design of intervention strategies to improve anti-angiogenic outcomes in patients with advanced cancers." (PMID 26159543, 2015). "Pan-cancer analysis showed significant upregulation of NRP1 in 10 solid tumor types and revealed co-expression relationships between NRP1 and 340 ATGs." (PMID 41948345, 2026). "Here, we provide an overview of how these omics approaches have elucidated the function and regulation of NRP1 in cancer." (PMID 40277760, 2025). "Neuropilin-1 (NRP1), initially identified as a neuronal guidance protein, has emerged as a multifaceted regulator in cancer biology." (PMID 40277760, 2025). "Disruption of interactions within the VEGF/NRP1 axis has the potential to impede the invasion and metastasis of cancer cells." (PMID 40048021, 2025). "Blocking NRP-1 resulted in the downregulation of EMT markers (e.g., N-cadherin, vimentin) and the upregulation of E-cadherin, suggesting that NRP-1 plays an important role in cancer progression and increased invasiveness." (PMID 40430075, 2025). "NRP1, as described in this review, can act as an important biomarker in multiple cancer types, and there is always an elevated expression of NRP1 in cancers." (PMID 40277760, 2025). "NRP1 is a versatile and multifunctional molecule that has gained significant attention as a potential target for cancer therapy." (PMID 40277760, 2025). "Deleting NRP-1 in preclinical models reduced migration, invasion, and angiogenesis, indicating its key role in cancer spread." (PMID 40430075, 2025). "The broad expression of CTSB and CTSL in other tissues and cell types aligns with their general role in proteolytic pathways, but their co-expression with NRP1 in macrophages hints at a cancer-specific regulatory network." (PMID 40134439, 2025). "Protein Expression Profiling: Mass spectrometry-based proteomics has quantified NRP1 protein levels in various cancer tissues and cell lines, confirming its overexpression in many malignancies." (PMID 40277760, 2025). "Given its multifaceted roles in cancer progression, NRP1 has surfaced as a potential target for therapeutic intervention." (PMID 40277760, 2025).
cancer (continued). "In other cancers, NRP1 modulates the polarization of TAMs towards pro-tumoral phenotype under hypoxia and contributes to immune evasion." (PMID 40805120, 2025). "Integrated omics approaches facilitate the identification of regulatory networks, and understanding how NRP1 interacts with other genes and proteins in regulatory networks helps delineate its role in cancer signaling pathways." (PMID 40277760, 2025). "The VEGF/NRP1 axis promotes the migration and invasion of cancer cells by enhancing the EMT process." (PMID 40277760, 2025). "NRP1 plays a pivotal role in cancer biology through its involvement in various cellular processes, including angiogenesis, immune modulation, and metastasis." (PMID 40277760, 2025). "Microarray and proteomics studies on Osteosarcoma (OS) revealed NRP1 as a major cancer cell migration and invasion regulator." (PMID 40277760, 2025). "Metabolomic profiling has shown that altering NRP1 expression affects the levels of various metabolites, linking NRP1 activity to metabolic reprogramming in cancer cells." (PMID 40277760, 2025). "Neuropilin-1 is henceforth a relevant target in cancer treatment; however, its way of action remains partly elusive, and the development of small inhibitory molecules is therefore required for its study." (PMID 40286084, 2025). "Investigation on the role of NRP-1 in anti-cancer immunotherapy found that NRP-1 restricts the renewal of exhausted T cells by downregulating Jun activation upon TCR restimulation." (PMID 39859271, 2025). "Treg cell expression of NRP1 differs significantly between mice and humans; NRP1+ Treg cell expression is higher in cancer patients." (PMID 40277760, 2025). "One such promising target is Neuropilin-1 (NRP1), a multifunctional transmembrane glycoprotein that has garnered significant attention recently because of its diverse roles in cancer biology." (PMID 40277760, 2025). "Transcriptomic analyses have provided insights into the expression patterns of NRP1 and its downstream targets across different cancers." (PMID 40277760, 2025). "Continued research using integrated omics approaches will further elucidate the complex roles of NRP1 in cancer biology and therapeutic response." (PMID 40277760, 2025). "This article explores the intricate relationship between NRP1 and cancer, highlighting its potential as a therapeutic target." (PMID 40277760, 2025). "Amongst the 19 cancer cell types, ccRCC cases showed the highest mRNA of NRP1, while NRP2 was mostly expressed in SKCM samples." (PMID 40134439, 2025). "As research unravels its complexities, NRP1-targeted therapies promise to improve treatment outcomes and advance the fight against cancer." (PMID 40277760, 2025). "The mechanisms modulating NRP1 expression in cancer cells are still controversial, but NRPs serve as predictive biomarkers of drug response." (PMID 40277760, 2025). "This intricate VEGF‐A/NRP‐1 interaction has garnered significant attention within the field of cancer therapy research." (PMID 40152069, 2025). "Omics technologies have significantly advanced our understanding of NRP1’s roles in cancer, from genetic alterations and expression patterns to protein interactions and metabolic effects." (PMID 40277760, 2025). "NRP1+ Treg cells are present across many cancers, both intratumorally and peripheral sites, indicating the capability of intratumoral Treg cell fitness." (PMID 40277760, 2025). "Another study by our group demonstrated that NRP1 knockdown in cancer cells depends on the genetic status of KRAS." (PMID 40277760, 2025). "Biomarkers: Integrated omics can uncover biomarkers for patient stratification, aiding in developing personalized cancer therapies based on NRP1 activity." (PMID 40277760, 2025). "Despite challenges in specificity and delivery, advances in understanding NRP1 biology offer new avenues for personalized cancer therapy." (PMID 40277760, 2025).
cancer (continued). "The ability of sNRP1s to sequester VEGF165 prevents it from interacting with cancer cells and other cells that express NRP1." (PMID 40277760, 2025). "Targeting NRP1 in cancer therapy involves several strategies, including the use of monoclonal antibodies, small molecule inhibitors, and peptide-based therapeutics designed to block its interaction with ligands and co-receptors." (PMID 40277760, 2025). "The application of omics technologies—genomics, transcriptomics, proteomics, and metabolomics—has significantly advanced our understanding of NRP1’s multifaceted roles in cancer." (PMID 40277760, 2025). "In summary, NRP1 is a critical player in cancer biology, and its multifaceted role makes it an attractive target for therapeutic intervention." (PMID 40277760, 2025). "A recent study shows that NRP1 expression has been identified in the blood vessels in more than 98% of cancer cases." (PMID 40277760, 2025). "With an enhanced level of VEGF secretion and upregulation of NRP1, such molecular cascade would contribute significantly to the angiogenic processes within cancer cells." (PMID 40134439, 2025). "Continued research and development of NRP1-targeted therapies have the potential to impact the treatment of various cancers significantly." (PMID 40277760, 2025). "Combining data from genomics, transcriptomics, proteomics, and metabolomics provides a comprehensive view of NRP1’s role in cancer." (PMID 40277760, 2025). "Proteomic approaches have shed light on the protein expression, interactions, and post-translational modifications of NRP1 in cancer." (PMID 40277760, 2025). "NRP1 is a transmembrane glycoprotein that is overexpressed in cancer cell membranes and regulates the cell penetration ability of peptide drugs." (PMID 38255307, 2024). "Second, conditional knockout of NRP1 on T cells corroborated these findings in different mouse cancer models, resulting in higher CD8+ T cell infiltration into the TME." (PMID 38609390, 2024). "Above all, our data support and broaden the concept that the VEGFA/NRP-1/GAPVD1 axis targets the downstream Wnt/β-catenin signaling pathway in regulating cancer stemness in TNBC cells." (PMID 38169627, 2024). "Neuropilin-1 (NRP-1) is a multifunctional glycoprotein which can be overexpressed in many cancer cells." (PMID 39283414, 2024). "NRP1 overexpression in cancers spurred the development of vesencumab/MNRP1685A mAb to inhibit tumorigenesis." (PMID 39589827, 2024). "Inhibitors of the interaction between Neuropilin-1 (NRP-1) and Vascular Endothelial Growth Factor-A165 (VEGF-A165) hold significant promise as therapeutic and diagnostic agents directed against cancers overexpressing NRP-1." (PMID 39181965, 2024). "NRP1 depletion attenuated proliferation and migration ability of cancer cells in vitro and in vivo in multiple cancer models." (PMID 39256867, 2024). "We hence turned to a cohort of ccRCC patients that had undergone nephrectomy to explore the role of the SEMA3A/NRP1 pathway in human cancer immunity." (PMID 38609390, 2024). "Previous studies have confirmed that NE enters the cell by first binding to the NRP1 on the surface of tumors, and then interacts with specific domains to selectively eradicate cancer cells." (PMID 39068444, 2024). "In current studies, we revealed that adenosine derivatives CD-suppressed NRP1 expression in cancer cells, implying the therapeutic potential for anti-cancer." (PMID 38138098, 2023). "Neuropilin-1 (NRP1) has been reported to be expressed by cancer stem-like cells and to be involved in cell spreading." (PMID 37511335, 2023). "PRV-LAV can infect cancer cells via NRP1/EGFR signaling and induce cancer cells apoptosis via ER stress." (PMID 37891570, 2023). "CD44, as a prognostic marker, is of great significance for clinical diagnosis and cancer treatment, and Neuropilin-1(NRP1) is a checkpoint target with unique implications for cancer immunology and immunotherapy." (PMID 37251370, 2023).